RASSF1-AS1 (RASSF1 antisense RNA 1)
Synonyms: ANRASSF1
Gene: Long non-coding RNA gene on chromosome 3 (50,337,425 to 50,338,300, forward strand). Ensembl gene ENSG00000281358.
Diseases named in the same sentence as RASSF1-AS1 in open-access papers:
RASSF1-AS1 is named in the same sentence as 4 diseases in open-access papers, as found by Europe PMC text mining. Sharing a sentence is not in itself a finding about the gene and the disease.
RASSF1-AS1 shares sentences with these, for which no sentence is quoted: tumor (3 papers); cancer (2); breast carcinoma (1); prostate tumor (1).